SQSTM1 (sequestosome 1)
Diseases named in the same sentence as SQSTM1 in open-access papers (continued):
Sharing a sentence is not in itself a finding about the gene and the disease.
viral infection (19 papers, 2015 to 2025). "This study revealed that viral infection of cells deficient in optineurin, sequestosome 1 or NDP52 produce IFNβ excessively." (PMID 37352136, 2023). "It will be interesting to determine if these monocytes are expressing MVNP to investigate the relation between post-zygotic mutations and viral infection, as it was done for the SQSTM1 germinal mutation." (PMID 25241215, 2015). "While more data is needed, the potential significance of these early results involving the PAV-431 drug target is underscored by the loss upon viral infection, and return upon drug-treatment of infected cells, of p62/SQSTM1, an important regulator of autophagy." (PMID 38889796, 2024). "For example, PARP12 was identified as an interferon-induced gene playing a potential role in cellular defenses against viral infections; its association with p62/SQSTM1 correlates with increased NF-kB signaling, suggesting the contribution of PARP12 to inflammation." (PMID 32900001, 2020). "Thus, viral infection may further cause the degradation of SQSTM1 by the autophagic-lysosomal pathway." (PMID 29125860, 2017). "Collectively, these findings demonstrate that p72 present in ASFV virions can be ubiquitinated and recognized by SQSTM1/p62 through its UBA domain in the early phase of viral infection." (PMID 39688418, 2025). "Sqstm1(+/−) MEFs produced a significantly larger amount of IFNβ compared with Sqstm1(+/+) and Sqstm1(−/−) MEFs after viral infection." (PMID 37352136, 2023). "There was a clear correlation between the increase for ATG8-II accumulation and the decrease for SQSTM1 accumulation as well during viral infection of insect vectors." (PMID 29125860, 2017). "An autophagy inhibitor, 3-MA, strongly inhibited the conversion of ATG8-I to ATG8-II and the degradation of SQSTM1 during viral infection." (PMID 29125860, 2017). "At 48 hpi, we detected that the accumulation of SQSTM1 was significantly increased after BAF treatment during viral infection of VCMs." (PMID 29125860, 2017). "The treatment of lysosome inhibitor BAF suppressed such degradation of SQSTM1 during viral infection." (PMID 29125860, 2017). "Supporting a role for phagosome biogenesis and LAP in VAPA, the expression of genes involved in LAP, namely MAP1LC3B (microtubule-associated protein 1 light chain 3 beta) and SQSTM1 (sequestosome-1), was decreased in IAPA and CAPA compared to patients with viral infection alone." (PMID 38651925, 2024). "Additionally, autophagy genes IFI16, ZC3H12A, SQSTM1, WDR81, and PIK3R2 are associated with viral infection, including SARS-CoV-1 and were downregulated in this study when cells were treated with NIC." (PMID 37901834, 2023). "However, Sqstm1(−/−) cells readily induced cell death compared with Sqstm1(+/−) cells during viral infection." (PMID 37352136, 2023). "Moreover, the expression of the BoHV-1 gC gene and the BoHV-1 titer were significantly increased in SQSTM1-overexpressing cells during viral infection." (PMID 35259065, 2022). "The inhibition by CIGB-300 of SQSTM1 phosphorylation at Ser272 may reduce the accumulation of aggresomes, and thus attenuates lung inflammation and the fibrosis induced by viral infection." (PMID 34930105, 2021). "Therefore, the p62/SQSTM1-SMURF1 pathway demonstrates a novel ubiquitin-independent mechanism of selective autophagy in viral infection." (PMID 34206057, 2021). "However, at 48 hpi, western blot assay showed that the accumulation of SQSTM1 was significantly decreased during viral infection of VCMs." (PMID 29125860, 2017). "Moreover, we observed a decrease in SQSTM1/p62 levels in HSV-1-infected cells following MG132 treatment, a decrease that could be attributed to autophagy triggered by the cellular stress caused by both MG132 and the viral infection." (PMID 39120287, 2024). "Other genes that were down-regulated with viral infection (GOLGA2, IFI16, WDR81, HK2, SQSTM1, ULK1) remained down-regulated with NIC treatment (with and without virus)." (PMID 37901834, 2023).
viral infection (continued). "In addition to virus infection, the iron metabolism-related gene HFE can also bind to MAVS for SQSTM1/p62-mediated MAVS degradation via selective autophagy." (PMID 38965634, 2024). "More precisely, Sqstm1(+/−) cells overproduce IFNβ during a viral infection, but this is not the case in Sqstm1(−/−) cells." (PMID 37352136, 2023).
glioma (18 papers, 2016 to 2025). A benign or malignant brain and spinal cord tumor that arises from glial cells (astrocytes, oligodendrocytes, ependymal cells). "Among these, the autophagy associated genes DRAM1 and SQSTM1 encoding for the key regulator p62 are highly expressed in Glioma stem cells (GSCs), and modulate their migration and invasion capabilities." (PMID 30845654, 2019). "Genetic deletion of Par-4 using shRNA, CRISPR or siRNA inhibited LC3-II conversion and p62/SQSTM1 degradation in glioma cells induced by RSL3 and ML210, and erastin." (PMID 38886572, 2024). "For the glioma TCGA cohort, the risk score was calculated as follows: risk score = (0.6457 × PGAM5 expression) + (0.8062 × SQSTM1 expression) + (−0.4834 × ATG9A expression) + (−0.6285 × GABARAPL1 expression)." (PMID 36292980, 2022). "By applying the glioma patient database, we found that mRNA levels of PD-L1 were significantly positively correlated to those of p62 (i.e., SQSTM1)." (PMID 31850228, 2019). "EMAP-II up-regulated the expression of the proteins LC3-II/I, ATG7 and ATG5, but down-regulated P62/SQSTM1 expression in the U-87 and U-251 glioma cells, demonstrating that the antitumor activity results from the induction of autophagy, not apoptosis." (PMID 27242439, 2016). "In glioma, SQSTM1 could promote proliferation, invasion and mesenchymal transition, which accurately predicted the prognosis of patients." (PMID 36186436, 2022). "Moreover, assessing autophagy status through LC3B and SQSTM1/p62 expression could be a promising prognostic tool for glioma patients." (PMID 38203743, 2024). "In 39 glioma cases, we assessed the protein expression of autophagy markers LC3B, SQSTM1/p62, and DRAM by immunohistochemistry (IHC) and the mRNA expression of the autophagy genes PTEN, PI3K, AKT, mTOR, ULK1, ULK2, UVRAG, Beclin 1, and VPS34 using RT-qPCR." (PMID 38203743, 2024). "RSL3 treatment of Par-4-overexpressing glioma cells showed a marked increase in LC3-II conversion and p62/SQSTM1 degradation." (PMID 38886572, 2024). "Among the 39 glioma cases analyzed, 23 (59%) cases of HGGs showed a positive expression of LC3B, whereas SQSTM1/p62 demonstrated positive expression in all 20 (100%) HGG cases." (PMID 38203743, 2024). "In 2019, Danni Deng demonstrated that the increase in p62 (an autophagy adaptor) expression, also known as sequestosome-1 (SQSTM1), promotes the advancement of glioma cell lines." (PMID 39485747, 2024). "The dissection of target molecules downstream of PD-L1 signaling has been advanced in PD-L1-overexpressed U251 glioma cells, in which expression was positively correlated with the PI3K/Akt pathway, p62/SQSTM1, and β-actin." (PMID 37834467, 2023). "We are trying to elucidate the mechanism how SQSTM1/p62 increases AEG-1 and junctional proteins through Epithelial-Mesenchymal Transition factors in TGF-β1-treated glioma cells." (PMID 26909607, 2016). "Notably, the key regulator of selective autophagy p62/SQSTM1 and DNA damage-regulated autophagy modulator 1 (DRAM1) are both highly expressed in glioma CSCs (GSCs)." (PMID 37886168, 2023). "As expected, overexpression of ASCL2 caused increased autophagic flux, as evidenced by conversion from LC3‐I to LC3‐II and degradation of SQSTM1 in multiple glioma cells, but did not significantly affect ATG7 and BECN1." (PMID 35882624, 2022). "Furthermore, similar to Bafilomycin A1 and chloroquine, NTZ impaired late-staged acidification of autophagosomes in lysosomes with increased expression of SQSTM1 and LC3 II, which suggests a novel role of NTZ as an autophagy inhibitor in glioma." (PMID 30302016, 2018). "In addition, PD-L1 expression was significantly positively correlated with PI3K (p = 0), SQSTM1 (p62, a negative marker of autophagic influx signaling) (p = 0) and ACTB (β-actin) (p = 0) in human glioma tissues." (PMID 31850228, 2019).
Alzheimer disease (17 papers, 2013 to 2024). A progressive, neurodegenerative disease characterized by loss of function and death of nerve cells in several areas of the brain leading to loss of cognitive function such as memory and language. "SQSTM1 and HSPA5 dysregulation has been implicated in neurodegenerative disorders, such as Alzheimer’s disease and Parkinson’s disease." (PMID 37059365, 2023). "Lastly, mice deprived of Sqstm1 display tau hyperphosphorylation and memory impairments, both hallmarks of Alzheimer’s disease, while Sqstm1 knock-down in zebrafish determines the development of locomotory impairments associated with autophagy defects and MN axon shortening." (PMID 35708843, 2022). "A link between neurodegenerative disorders and defective autophagosome transport or p62/SQSTM1 accumulation as a major pathological feature has been described, as well as a signal crosstalk between autophagy and apoptosis in regulating the pathogenesis of Alzheimer’s disease (AD)." (PMID 39367928, 2024). "The role in inverse comorbidity of cancer and Parkinson’s disease/Alzheimer’s disease was shown for APOE, APOC1, SQSTM1, PSEN1, and SP1." (PMID 37298337, 2023). "The aim of this study was to further investigate the role of genes identified in our previous studies as relevant for the pathophysiology of Alzheimer’s disease and T2DM comorbidity, namely ATG16L1, ATG16L2, GABARAP, GABARAPL1, GABARAPL2, and SQSTM1." (PMID 36901549, 2023). "Among the genes highlighted in the network analysis, four were also confirmed in the Alzheimer’s disease animal models: ATG3, GABARAPL2 (ATG8), MAP1LC3B, and SQSTM1." (PMID 30850634, 2019). "Sequestosome 1 (SQSTM1)/p62 is a multifunctional scaffolding protein and plays a major role in the cellular processes of autophagy, upregulation of which has been shown in several neurodegenerative disorders, including Alzheimer’s disease (AD)." (PMID 35296031, 2022).
Parkinson disease (16 papers, 2013 to 2025). A progressive degenerative disorder of the central nervous system characterized by loss of dopamine producing neurons in the substantia nigra and the presence of Lewy bodies in the substantia nigra and locus coeruleus. "Secondly, Cluster#2, "Intracellular Organelle" is influenced by several clusters, including "Pink1-associated Parkinson's Disease", "Mitochondrial Dynamics", "SQSTM1 Cooperation", "Mitochondrial Fission" and "Small N-terminal Tag"." (PMID 41267150, 2025). "Mutations in p62/SQSTM1 are known to be associated with ALS and frontotemporal dementia (FTD), as well as with some forms of Parkinson disease through a role in mitophagy." (PMID 33557921, 2021). "SQSTM1 has been associated with many other neurodegenerative diseases, including Alzheimer’s, Parkinson’s and Huntington disease, where p62/SQSTM1 is a predominant component of the toxic inclusions formed in the neurons." (PMID 28878620, 2017). "Homozygous mutations in SQSTM1 lead to a congenital absence of the autophagy receptor and cause a childhood-onset neurodegenerative condition with a phenotype comprising ataxia/cerebellar syndrome, parkinsonism, and cognitive decline." (PMID 34130600, 2022). "CGA also modulated the expression of genes related to Parkinson’s disease and autophagy, including α-synuclein (α-syn), LC3B, SQSTM1, ATG5, ATG7, and ULK1B, thereby indicating its capacity to enhance autophagy in Parkinson’s disease pathogenesis." (PMID 41142236, 2025). "The importance of mitophagy in the pathogenesis of neurodegenerative diseases is supported by the identified mutations of proteins involved in mitophagy—primarily PINK1 and parkin in Parkinson’s disease, optineurin and TBK1 in amyotrophic lateral sclerosis, and p62/SQSTM1 in frontotemporal dementia." (PMID 34638589, 2021). "Moreover, EV populations associated with α‐synuclein release and intercellular transfer are enriched for p62/SQSTM1 and lipidated LC3, and secretion of these autophagic proteins is dramatically increased in the cerebrospinal fluid of Parkinson's disease patients." (PMID 33977236, 2021).
glioblastoma (15 papers, 2013 to 2025). The most malignant astrocytic tumor (WHO grade IV). "Hence, autophagy dysregulation via ATG12 gene knockdown or p62/SQSTM1 deficiency reduced invasion and migration phenotypes in glioblastoma cells." (PMID 35359388, 2022). "•Hypoxia upregulates HIF-1α but downregulates Nrf2 and p62/SQSTM1 in human glioblastoma U373-MG and T98G cells." (PMID 41103582, 2025). "SQSTM1 has been found to be overexpressed in several types of cancer, including glioblastoma and melanoma." (PMID 34287356, 2021). "It was also reported that DRAM1 and SQSTM1 regulated cell migration and invasion of glioblastoma stem cells." (PMID 23696801, 2013). "Moreover, SQSTM1/p62 has been described to cooperate with NRF2 signaling to sustain the expression of EMT-TFs in a mesenchymal glioblastoma subtype." (PMID 34944948, 2021). "However, in a state of oxidative stress, autophagy activated by oxidative stress was found to cause depletion of SQSTM1 in HeLa cells and glioblastoma cell lines, independent of ubiquitin proteasome and transcription." (PMID 36851605, 2023). "Interestingly, the inhibition of the WNT pathway increases the expression of SQSTM1 in glioblastoma cells and sensitizes the tumor cells to the autophagy inhibitor effects, and therefore could offer an alternative therapy." (PMID 33525678, 2021). "Interestingly, the expression of SQSTM1 in glioblastoma cells is increased with the inhibition of the WNT pathway, sensitizing tumor cells to the effects of autophagy inhibitors and thus could offer an alternative therapy for this cancer type." (PMID 32707662, 2020). "miR-93 was shown to control autophagic activity in GSC glioblastoma stem cells by inhibiting BECN1/Beclin 1, ATG5, ATG4B, and SQSTM1/p62." (PMID 36834933, 2023). "Downregulating the autophagy players DRAM1, SQSTM1 and ATG7 impaired the capacity of patient-derived, mesenchymal-like GSCs to invade using a transwell cell culture system, supporting a role for autophagy in glioblastoma invasion." (PMID 32873152, 2020). "Next, to better clarify the action of RDS 3337 in the autophagic process in U87 glioblastoma cells, we verified the autophagic flux using 100 nM BafA1 for 2 h, which prevents lysosomal acidification and, as a consequence, accumulates LC3-II by inhibiting p62/SQSTM1 degradation." (PMID 37508554, 2023).
melanoma (15 papers, 2016 to 2025). A malignant, usually aggressive tumor composed of atypical, neoplastic melanocytes. "We found that knocking down ALKBH5 resulted in a decrease in SQSTM1 protein expression, which was negatively correlated with the degree of cell autophagy, promoting autophagy in A375 and A2058 melanoma cells." (PMID 38481816, 2024). "A previous study reported the ability of SQSTM1 to extend the mRNA half-life of pro-metastatic factors in melanoma cells and mediate the epithelial-to-mesenchymal transition in nasopharyngeal carcinoma cells." (PMID 35436939, 2022). "However, in different experimental settings of autophagy stimulation, concomitant transcriptional induction of the SQSTM1 gene occurs, as documented also by us in trehalose-treated melanoma cells." (PMID 41103582, 2025). "An autophagy-independent role of p62/SQSTM1 has been ascribed to the control of melanoma metastasis by recruiting RNA-binding proteins in cooperation with insulin-like growth factor 2 mRNA-binding protein 1 (IGF2BP1) to stabilize transcripts of a number of pro-metastatic factors." (PMID 32340261, 2020). "In addition to BECN1 inhibition, targeting other autophagy-related molecules, such as ATG5 or p62/SQSTM1, or inhibiting melanoma autophagy pharmacologically by chloroquine can similarly induce the expression of CCL5 in melanoma cells and consequently enhance the antitumor capacity of NK cells." (PMID 36003368, 2022). "WX8 disrupted autophagy in melanoma tumors, as evidenced by increased levels of LC3‐II and SQSTM1 proteins and RNA." (PMID 38414326, 2024). "SIRT6 knockdown was found to cause a marked decrease in the protein levels of LC3 II (autophagy related form of LC3), ATG3, ATG7, SQSTM1 and BECN in melanoma cells." (PMID 29234488, 2017). "Inhibition of melanoma autophagy through targeting at ATG5, p62/SQSTM1 and BECN1 activates MAPK8/JNK-JUN/c-Jun signaling pathway in melanoma cells which up-regulates CCL5 cytokine in the TME and thus enhance NK function via activation of NK cell activator NKp46." (PMID 36003368, 2022). "On the other hand, a recent report showed that Alteronol at 1–2 μM concentrations induced autophagy response in malignant melanoma A375 and UACC62 cells, as evidenced by LC3B processing and cellular re-distribution, SQSTM1/p62 protein degradation and autophagic vacuole formation." (PMID 33224877, 2020). "In line with this idea, a very recent work indicates that the well-known autophagy receptor Sqstm1/p62 is involved in fueling melanoma progression through a distinct non-autophagy pathway." (PMID 31998652, 2019). "Hypoxia-induced autophagy in melanoma cells leads to STAT3-mediated suppression of the tumor-lysing function of cytotoxic T cells, while inhibiting melanoma autophagy restores CTLs’ function through ubiquitin proteasome system and SQSTM1/p62 involved down-regulation of phospho-STAT3." (PMID 36003368, 2022).
pancreatic cancer (14 papers, 2013 to 2025). "In RAS-mutated pancreatic cancer cells, the inhibition of autophagy activated the SQSTM1/p62-mediated NF-kappa-B pathway, subsequently enhancing EMT which finally promoted cancer invasion." (PMID 36263211, 2022). "Using 40 cases of tumor tissue chip, elevated SQSTM1 expression was mainly observed in the cytoplasm of pancreatic carcinoma cells and differently expressed among the T stages." (PMID 35957699, 2022). "Treatment with IMB-6G leads to substantial accumulation of both LC3-II and p62/SQSTM1 in pancreatic cancer cells." (PMID 28139733, 2017). "Mechanistically, manzamine A exerted its effects via increasing LC3-II and p62/SQSTM1 in pancreatic cancer cells." (PMID 25402829, 2014). "Hence, to confirm the autophagic nature of the observed vacuoles in RCE-treated human pancreatic cancer cells, we examined the protein levels of autophagy markers p62 (Sequestosome 1) and LC3-II." (PMID 39139643, 2024). "Thus, genetic inactivation of E4f1 has been shown to induce autophagy in leukemic cells and MDM2 was also shown to be regulated upon accumulation of the autophagy substrate p62/SQSTM1 in KRASG12D-driven pancreatic cancer cells." (PMID 33406607, 2021). "Autophagy-induced apoptosis was associated with parthenolide treatment in triple-negative breast cancer cells and pancreatic cancer cells by increasing the expression of beclin-1, LC3II, and p62/SQSTM1." (PMID 37298119, 2023). "In pancreatic cancer cells, 10 μM manzamine A affected vacuolar ATPase activity and significantly increased the level of autophagosome marker LC3-II and p62/SQSTM1 as observed by western blot analysis." (PMID 24048269, 2013). "Additionally, to confirm whether THM induced autophagy in pancreatic cancer cells, we further assessed the expression levels of multiple autophagy-related proteins, including ATG5, ATG7, LAMP2, SQSTM1 and LC3B, in THM-treated cells." (PMID 40756353, 2025).